MIR6862-1 (microRNA 6862-1)
Synonyms: hsa-mir-6862-1
Gene: MicroRNA gene on chromosome 16 (28,390,982 to 28,391,051, reverse strand). Ensembl gene ENSG00000275429.
Homologues: Paralogues in human: MIR6862-2 (100% identical).